MMP2 (matrix metallopeptidase 2)
Diseases named in the same sentence as MMP2 in open-access papers (continued):
Sharing a sentence is not in itself a finding about the gene and the disease.
Marfan syndrome (7 papers, 2015 to 2025). A disorder of the connective tissue. "MMPs (matrix metalloproteinases) are proteinases involved in fragmentation of elastic fibers in Marfan syndrome, with MMP-2 and MMP-9 specifically involved in the pathogenesis of Marfan aneurysm formation." (PMID 36140728, 2022). "Although none of these studies reported independent associations between circulating MMP-3 and cfPWV, 1-year treatment with perindopril, compared to placebo, was associated with a significant reduction in cfPWV as well as in plasma MMP-2 and plasma MMP-3 in 17 patients with Marfan Syndrome." (PMID 29070037, 2017). "Furthermore, although differences in the expression levels of FBN1-related genes, such as TGFb and MMP2, were observed in our FBN1 het KO samples, these discrepancies were not identical to those observed in Marfan syndrome." (PMID 32210272, 2020).
medulloblastoma (7 papers, 2014 to 2024). A malignant, invasive embryonal neoplasm arising from the cerebellum. "In this current study, we have advanced the understanding of the mechanism of action of MMP-2 and its inducer EMMPRIN in medulloblastoma progression by demonstrating that MMP-2 and EMMPRIN are associated with secreted exosomes." (PMID 37174066, 2023). "This study demonstrates the importance of EMMPRIN and MMP-2-associated exosomes in creating a favourable environment to drive medulloblastoma metastasis via extracellular matrix signalling." (PMID 37174066, 2023). "Importantly, this study found a high level of MMP-2 activity in CSF from three of four patients associated with tumor progression, suggesting that MMP-2-expressed EVs may modulate the PMN to drive medulloblastoma metastasis." (PMID 38730633, 2024). "When it comes to medulloblastomas, the literature is more limited; however, a study indicated that VM was present in about 22% of the examined medulloblastoma tissues and was associated with higher expression of matrix metalloproteinases (MMP-2, MMP-14), ephrin (Eph) A2, and laminin 5γ2." (PMID 33036204, 2020). "Our observations also highlight the potential of MMP-2 as a biomarker for metastatic medulloblastoma." (PMID 37174066, 2023). "Having been shown to correlate with poor patient outcomes and a higher grade in multiple cancers, it was postulated that the expression of MMP-2 would represent a poor prognosis factor in medulloblastoma." (PMID 37174066, 2023). "Although some studies have already demonstrated the tumour-supporting functions of EMMPRIN or MMP-2 in medulloblastoma metastasis, the presence of these proteins on medulloblastoma exosomes has not yet been investigated." (PMID 37174066, 2023). "In group four, medulloblastoma cells’ knockdown of BSG or MMP-2 at the genetic level resulted in a reduction of the ability of cells to invade a collagen-IV–laminin matrix." (PMID 37174066, 2023). "MSCs have been show to upregulate tumor growth by migrating to the developing intrahepatic cholangiocarcinoma via SDF-1/CXCR4 signaling pathway, and MMP2 molecular factor in human medulloblastoma." (PMID 30513684, 2018). "Immunohistochemical studies have revealed that the presence of VM is associated with the expression of MMP-2, MMP-14, EphA2 and laminin 5γ2 in medulloblastoma." (PMID 25202424, 2014). "Degradation of the ECM would create routes for medulloblastoma cells to directionally invade the surrounding environment, and functional MMP-2 on the external surface of exosomes could allow exosomes to reach long-distance target locations." (PMID 37174066, 2023). "Given that exosomes from metastatic medulloblastoma cells, carrying higher levels of MMP-2 and EMMPRIN could confer an invasive phenotype on recipient cells, we decided to test the direct contribution of MMP-2 and EMMPRIN by genetic knockdown." (PMID 37174066, 2023). "In addition, the preconditioning with exosomes isolated from MMP-2 knockdown cell lines also reduced the secretion of MMP-2 in primary medulloblastoma cell lines compared to controls." (PMID 37174066, 2023). "The association between exosomal EMMPRIN/MMP-2 and ECM degradation was reinforced by zymography assays, demonstrating that secretion of active MMP-2 was activated in primary medulloblastoma cell lines upon coculture with metastatic exosomes enriched with high glycosylated EMMPRIN and MMP-2." (PMID 37174066, 2023). "However, when medulloblastoma patients were stratified according to mRNA levels at diagnosis, those with elevated MMP-2 expression displayed a better five- and ten-year overall survival than patients with low MMP-2 expression." (PMID 37174066, 2023). "Since EMMPRIN is known to induce MMP-2 production and secretion, it was slightly surprising that an increase in MMP-2 function was observed when primary medulloblastoma cell lines were preconditioned with exosomes isolated from BSG knockdown cell lines, (Figure 5Fii)." (PMID 37174066, 2023).
medulloblastoma (continued). "It would be interesting to see if this protein corona is present in medulloblastoma-derived exosomes and if MMP-2 or EMMPRIN might either be interacting with it or constituting it." (PMID 37174066, 2023). "Furthermore, metastatic exosomes were shown to potentiate medulloblastoma migration resulting in the degradation of the extracellular matrix components, via the active protease, MMP-2, on their surface." (PMID 37174066, 2023). "However, this “high is worse” pattern was observed at the protein level, indicative that MMP-2 protein levels may be a more physiologically relevant marker of medulloblastoma metastasis." (PMID 37174066, 2023). "Finally, we observed increased levels of functionally-active MMP-2 in medulloblastoma patients’ CSFs, which correlated with disease progression and appeared to correlate with prognosis, highlighting the biomarker potential of functional MMP-2." (PMID 37174066, 2023). "Together, these results indicate that exosomal EMMPRIN has the ability to initiate MMP-2 secretion in the recipient medulloblastoma cells, while exosomal MMP-2 can further stimulate MMP-2 secretion in a positive feedback loop." (PMID 37174066, 2023). "In support of this, stable genetic knockdown of the genes encoding MMP-2 and EMMPRIN (namely MMP-2 or BSG) antagonised the promigratory function of exosomes, confirming that MMP-2 and EMMPRIN are promigratory factors on medulloblastoma exosomes." (PMID 37174066, 2023). "In accordance with the findings that depletion of MMP-2 or EMMPRIN slightly reduced migration of medulloblastoma cells, these results strongly indicate that exosomal MMP-2 and EMMPRIN facilitate the progression of medulloblastoma." (PMID 37174066, 2023). "Metastatic exosomes were shown to potentiate medulloblastoma migration via the active protease, matrix metalloproteinase-2 (MMP-2), on their surface, resulting in degradation of the extracellular matrix (ECM) and creating routes for medulloblastoma cells to invade into the surrounding environment." (PMID 37174066, 2023). "Additionally, when comparing MMP-2 gene expression in matched-primary and metastatic medulloblastoma cell lines there was not a consistent pattern of high MMP-2 in metastatic cells and low MMP-2 expression in the primary cells." (PMID 37174066, 2023).
Miscarriage (7 papers, 2011 to 2026). A pregnancy that ends at a stage in which the fetus is incapable of surviving on its own, defined as the spontaneous loss of a fetus before the 22th week of pregnancy. "Other studies showed that increasing MMP9 and the MMP2/TIMP 2 ratio increased the risk of miscarriage." (PMID 36910123, 2022). "Multivariate logistic regression analysis by adjusting for all these variables (age, BMI, gestational days, RBC, WBC, Hb, smoking, and drinking) showed that the protein levels of MMP‐2, NDST1, and TSPAN4 were positively associated with miscarriage." (PMID 41168951, 2026). "AUB women with miscarriage history showed upregulation in MMP2, TGFB3 (P < 0.05), and downregulation in MMP9 and VEGFB (P < 0.05) expression compared to AUB group with no miscarriage history." (PMID 36564776, 2022). "Excessive TIMP2 expression disrupts the fine-tuned MMP2/TIMP2 balance, leading to abnormal ECM degradation in the endometrium, which interferes with embryo implantation and normal placental development, potentially causing spontaneous miscarriage." (PMID 40151207, 2025). "AIT inhibits ERK/MMP-2 and MMP-9 pathways through PD-L1 reduction, attenuates embryonic trophoblast invasion and ultimalely induces miscarriage ultimately." (PMID 31656199, 2019). "Relative expression of MMP2 (0.15 ± 0.01) and TGFB3 (0.79 ± 0.02) increased significantly (P < 0.01) in AUB females with miscarriage history compared to AUB females with no miscarriage (0.07 ± 0.01, 0.11 ± 0.01) history respectively." (PMID 36564776, 2022).
neuropathic pain (7 papers, 2012 to 2024). Chronic pain caused by damage to nerve fibers. "MMP-9 induces early-phase neuropathic pain by activating interleukin (IL)-1β and microglia in the early phase, while MMP-2 is implicated in the development of late-phase neuropathic pain." (PMID 39654618, 2024). "In the context of neuropathic pain, elevated MMP-2 contributes to the development of neuropathic pain." (PMID 33841531, 2020). "Previous studies have shown that MMP-9 and MMP-2 have been considered key molecules for the onset and maintenance of neuropathic pain inhibition of astrocytes activation and could effectively attenuate neuropathic pain." (PMID 28859670, 2017). "While a pathophysiological role of MMP-2 and MMP-9 has been demonstrated in neuropathic pain, the relevance of these metalloproteinases in chronic inflammatory pain is still elusive." (PMID 22353423, 2012). "Of the 47 investigated proteins, 21 (cathepsin S, CCL2, CCL4, CCL16, CFIII, CXCL5, cystatin B, E-Selectin, Fas/TNFRSF6, follistatin, GDF-15, GH, ICAM1, IL8, KLK5, MMP2, MMP9, P-Selectin, sortilin, TIMP4 and VEGF) were detectable by multiplex SP-PLA in ≥ 95% of the neuropathic pain patient samples." (PMID 26914813, 2016).
proliferative diabetic retinopathy (7 papers, 2008 to 2025). Advanced retinopathy due to diabetes mellitus characterized by the formation of new vessels in the retina. "In proliferative diabetic retinopathy, the elevated levels of MMP-2 and MMP-9 were shown to cause ECM remodeling further leading to net collagen IV degradation and vitreous liquefaction." (PMID 29312345, 2017). "Upregulated MT1-MMP, with other proangiogenic factors such as MMP-2 and MMP-13, are associated with various progressive diseases, including tumor invasion, corneal neovascularization, and proliferative diabetic retinopathy via active neovascularization." (PMID 36768503, 2023). "MMP-2 expression was detected in endothelial cells of retinal neovessels from proliferative diabetic retinopathy (PDR) patients, whereas MMP-2 protein levels were elevated in the aqueous humor of PDR patients compared with healthy patients." (PMID 25723058, 2014). "Our current clinical results, supported by the relatively scarce literature, indicate that MMP-2 may play a role the pathogenesis of proliferative diabetic retinopathy." (PMID 25848912, 2015). "The objective of the present study was to test for a possible association of five single nucleotide polymorphisms (SNPs) in the MMP-2 gene and two polymorphisms in the MMP-9 gene with proliferative diabetic retinopathy (PDR) and to determine their plasma levels." (PMID 18552985, 2008). "In this study, we emphasize the significance of the in vitro findings by analyzing the effects of DXC on the retinal activity and expression of MMP-2 in a mouse model of OIR which reproduces neovascular disorders such as retinopathy of prematurity and proliferative diabetic retinopathy." (PMID 40230413, 2025).
renal failure (7 papers, 2016 to 2024). "In another study, renal insufficiency significantly increased local levels of MMP-2." (PMID 27764090, 2016). "Interestingly, higher levels of MMP-2 and TIMP-2 were found in serum from patients with CKD, and serum levels of MMP-2 were correlated with the degree of kidney failure." (PMID 39769454, 2024).
Ureteral obstruction (7 papers, 2014 to 2024). Obstruction of the flow of urine through the ureter. "Kidney fibrosis is attenuated under conditions of unilateral ureteral obstruction in mice with reduced MMP-2 production due to a deficiency in the MMP-2 inducer Basigin, and MMP-2 knockout in mice also results in reduced kidney fibrosis under conditions of unilateral ureteral obstruction." (PMID 38610646, 2024). "In contrast, Ybx1ΔRosaERT+TX knockout animals displayed fewer MMP2 transcripts and reduced enzymatic activity compared to wild-type animals, especially on day 14 of ureteral obstruction." (PMID 38474331, 2024). "MMP-2 expression increased significantly after ureteral obstruction at d7 and d14 in WT and Tlr2-/- mice, with a slightly increasing trend for Tlr2-/- kidneys, but without significant differences between the two lines." (PMID 38015955, 2023). "In a previous study, for example, there was an early increase in MMP2 expression and activity in a unilateral ureteral obstruction model." (PMID 29464020, 2018). "The clinical treatment of ureteral obstruction is primarily surgical, but as a strategy for limiting the destruction of kidney tissue in progressive or recurring disease, some intervention against Mmp2 may be useful." (PMID 26673451, 2015).
amyloid (6 papers, 2014 to 2025). "Thus, the up-regulation of ANGPT1, SORCS2 and MMP2 in AD ONS cells is consistent with enhanced amyloid-associated degenerative effects." (PMID 36291125, 2022). "In AD patients, there was an increase in MMP-2 expression in astrocytes surrounding amyloid plaque and a decrease in the MMP-2 plasma level compared to controls." (PMID 33986628, 2021). "The activity of MMP-2/9 increases with amyloidosis and advancing age within the aortic wall which is linked to increased Ang II/MFG-E8/medin signaling." (PMID 29085385, 2017). "In addition, MMP2 and MMP9 levels have been shown to be associated with cerebral hemorrhage resulting from vascular amyloid deposition (that is, CAA)." (PMID 24991237, 2014). "Incubation of fresh slices for 2 weeks with 1–0.1–0.01 μg/ml of NEP, insulysin, MMP-2, or MMP-9 showed that NEP, insulysin, and MMP-9 markedly degraded beta-amyloid plaques but only at the highest concentration." (PMID 25914642, 2015).
Anxiety (6 papers, 2016 to 2026). Intense feelings of nervousness, tension, or panic often arise in response to interpersonal stresses. "MMP2 interacts with paclitaxel, a commonly used chemotherapy medication, and induces anxiety-like behavior in mouse." (PMID 34997195, 2022). "MMP2 KO mice were found to exhibit increased anxiety and differences in motor activities in behavioral tests, suggesting that MMP2 plays an important role in cognitive and motor behaviors." (PMID 33396569, 2020). "Basal CRP, IL-6 andTNF-α, as well as most individual LPS-stimulated inflammation markers (IL-6,IL-8, IL-10, IL-18, MCP-1, MIP-1α, MIP-1β, MMP2 and TNF-β) weresignificantly associated with depressive and anxiety symptom severity." (PMID 27244234, 2016). "Unlike basal inflammation, LPS-stimulated inflammation was stillassociated with (anxiety) symptom severity after adjustment for lifestyle and health(IDS: IL-8, MCP-1, MMP2; BAI: LPS index, IL-6, IL-8, IL-10, IL-18, MCP-1, MMP2,TNF-β)." (PMID 27244234, 2016).
apical periodontitis (6 papers, 2012 to 2025). "In an animal study, MMP-9 and MMP-2 have a strong correlation with progression of apical periodontitis." (PMID 36012195, 2022). "Many studies have demonstrated that MMP-2 expression and activity are elevated in apical periodontitis and have been suggested to play a key role in the progression of this disease." (PMID 30213073, 2018). "Matrix metalloproteinase-2 (MMP-2) expression and activity are elevated in apical periodontitis and have been suggested to participate in bone resorption." (PMID 30213073, 2018). "MMP-9 and MMP-2 have been identified through immunohistochemistry in experimentally-induced apical periodontitis in animal models where they were proposed to play a role in both, the initiation and progression of apical periodontitis." (PMID 22436166, 2012). "Studies observing a significant increase in the expression levels of MMP-1, MMP-2, MMP-3, MMP-7, MMP-9, and TIMP 1 could be related to an individual predisposition to apical periodontitis (AP)." (PMID 40725414, 2025). "The level of MMP-2 in root canal exudate of teeth with pulp necrosis or asymptomatic apical periodontitis is reduced gradually with root canal treatment procedures, which might validate MMP-2 as a biomarker." (PMID 36012195, 2022). "Some SNPs in the MMP-2 and MMP-3 genes have been studied, testing the hypothesis that these SNPs could be associated with increased susceptibility to apical periodontitis (AP), thereby contributing to different stages of the inflammatory process, bone remodeling, and tissue regeneration." (PMID 40725414, 2025). "Therefore, inhibiting MMP-2 activation may be considered a therapeutic strategy for treating apical periodontitis." (PMID 30213073, 2018).
brain cancer (6 papers, 2014 to 2021). A primary or metastatic malignant neoplasm affecting the brain. "The nanosystem conjugated with chlorotoxin (Cltx), which expressed the specific binding to matrix metalloproteinase-2 (MMP-2), a receptor overexpressed on the brain cancer cells." (PMID 32194864, 2020). "Notably, hypoxia has also been shown to activate MMP-2, -9 and -13 in brain tissues; however, the current study is the first to demonstrate that these proteases may be TLR9-regulated in brain cancer cells." (PMID 24959259, 2014).
brain edema (6 papers, 2014 to 2025). Increased intracellular or extracellular fluid in brain tissue. "This study was to explore the mechanisms underlying 1,2-dichloroethane (1,2-DCE) induced brain edema by focusing on alteration of matrix metalloproteinase-2 (MMP-2) in rat astrocytes induced by 2-chloroethanol (2-CE), an intermediate metabolite of 1,2-DCE in vivo." (PMID 28101000, 2016). "Clinical studies have observed that plasma MMP-2 levels in ICH patients correlate with cerebral edema severity and neurological outcome, suggesting its involvement in acute injury processes." (PMID 41480312, 2025). "This reduction in MMP-2 levels correlated with increased severity of cerebral edema and worse neurological outcomes." (PMID 41480312, 2025). "AQPs, like MMP2, play essential roles in the pathogenesis of brain edema." (PMID 24828425, 2014). "Taken together, it was of interest to investigate the involvement of MAPK signal pathways in modulation of MMP-2 expression in 2-CE treated astrocytes, which would contribute to identify new therapeutic targets for 1,2-DCE induced brain edema." (PMID 28101000, 2016). "In addition, acupuncture or EA at the Baihui (GV20) and left Zusanli (ST36) acupoints in rat model significantly reduces the expression of the proinflammatory enzyme MMP2 and the water channel proteins AQP4, to relieve inflammation related brain edema." (PMID 30356696, 2018). "It has been reported that in most cases, the inhibitory effects on expressions of MMP-2 and MMP-9 could reduce the permeability of BBB at the early phase of brain edema formation." (PMID 28101000, 2016).
chronic rhinosinusitis (6 papers, 2016 to 2023). Chronic form of sinusitis. "In addition, vitamin D inhibited the expression and activity of MMP-9 in human lung fibroblasts and MMP-2 in patients with chronic rhinosinusitis." (PMID 36845046, 2023). "Pathogenesis of chronic rhinosinusitis might also be related to the regulation of MMP-2 and TIMP-2 expressions." (PMID 33777140, 2021). "CSE may contribute to the pathogenesis of chronic rhinosinusitis by regulating MMP-2 and TIMP-2 expression." (PMID 32806646, 2020). "S. aureus has been shown to induce the tissue remodeling factors MMP2, MMP9, and TIMP1 in mucosal explants from chronic rhinosinusitis (CRS) patients." (PMID 28083514, 2016).